JAK1 (Janus kinase 1)
Diseases named in the same sentence as JAK1 in open-access papers (continued):
Sharing a sentence is not in itself a finding about the gene and the disease.
myelofibrosis (continued). "Ruxolitinib is the only effective small-molecule JAK1/2 selective inhibitor approved by the US Food and Drug Administration (FDA) for myelofibrosis treatment in 2011." (PMID 35382859, 2022). "For instance, selective JAK1 and JAK2 Ruxolitinib has been shown to reduce VTE events in patients with polycythaemia vera and myelofibrosis." (PMID 36615007, 2022). "Ruxolitinib is an oral JAK1/2 inhibitor, recently FDA-approved for treatment use in myelofibrosis and polycythemia Vera." (PMID 35205818, 2022). "We used the JAK1 and JAK2 inhibitor ruxolitinib, which is approved for the treatment of myelofibrosis, polycythemia vera and acute graft-versus-host disease, where it primarily exerts cytoreductive and antiproliferative effects." (PMID 34769079, 2021). "Ruxolitinib is a potent, highly bioavailable JAK1/2 inhibitor that is already US Food and Drug Administration (FDA) approved for the treatment of myelofibrosis, polycythemia vera, steroid-refractory acute graft versus host diseases and atopic dermatitis." (PMID 34777398, 2021). "Ruxolitinib, which targets JAK1/JAK2 is used in the treatment of psoriatic arthritis, AD, and several lymphoid malignancies, e.g., myelofibrosis and polycythemia vera." (PMID 34948183, 2021). "Ruxolitinib is a potent JAK1 and JAK2 inhibitor, with good safety profile, that is approved for myelofibrosis and polycythemia vera, two myeloproliferative neoplasms characterized by over-inflammation." (PMID 32814839, 2021). "Then, we report a complex structure of DCLK1 kinase domain with the most potent inhibitor ruxolitinib, which has been originally developed as a Janus kinases (JAK1 and JAK2) inhibitor for treatment of myelofibrosis." (PMID 34445192, 2021). "The JAK1/2-selective inhibitor ruxolitinib is FDA approved for the treatment of polycythemia vera, myelofibrosis, and graft versus host disease, and it has been shown to decrease STAT3 activation in preclinical models of several solid tumors." (PMID 33521321, 2020). "Ruxolitinib (Jakafi or Jakavi) is a licensed, orally administered JAK1/JAK2 inhibitor used to treat neoplastic diseases, particularly myelofibrosis." (PMID 32101732, 2020). "Ruxolitinib, a potent inhibitor of JAK1/2, was approved by the FDA in the treatment of polycythemia vera and myelofibrosis." (PMID 32086862, 2020). "Accordingly, ruxolitinib is the only selective JAK1 and JAK2-inhibitor approved for the treatment of myelofibrosis and aGVHD." (PMID 33489899, 2020). "Ruxolitinib, a small-molecule inhibitor of JAK1/2, was the first FDA approved drug for the treatment of myelofibrosis." (PMID 31540495, 2019). "Ruxolitinib, an orally bioavailable and selective inhibitor of Janus kinase 1 (JAK1) and JAK2, significantly reduces splenomegaly and disease‐related symptoms in patients with myelofibrosis (MF)." (PMID 30997748, 2019). "Momelotinib (MMB; GS-0387; CYT387) is a JAK1 and JAK2 inhibitor, with therapeutic activity in myelofibrosis (MF), in humans as well as in mice." (PMID 29515114, 2018). "Ruxolitinib is a potent and selective oral JAK1 and JAK2 inhibitor that was FDA-approved in 2011 for the treatment of myelofibrosis (MF), post-polycythemia vera myelofibrosis (PPV-MF), and post-essential thrombocythemia myelofibrosis (PET-MF)." (PMID 29849942, 2018). "The JAK1 and JAK2 inhibitor ruxolitinib is approved for patients with myelofibrosis and with PV resistant or intolerant to hydroxyurea." (PMID 29228564, 2017). "Ruxolitinib is a selective inhibitor of JAK1 and JAK2 that is licensed to treat myelofibrosis and being evaluated in CLL." (PMID 27579615, 2016). "Ruxolitinib is a Janus kinase (JAK) (JAK1/JAK2) inhibitor that has demonstrated superiority over placebo and best available therapy (BAT) in the Controlled Myelofibrosis Study with Oral JAK Inhibitor Treatment (COMFORT) studies." (PMID 27211272, 2016).
myelofibrosis (continued). "The results are quite expected since AZD1480 is known to be a potent, selective JAK2 inhibitor, while ruxolitinib is a potent JAK1 and JAK2 inhibitor approved by FDA for treatment of myelofibrosis." (PMID 25036984, 2014). "MM implicates JAK1 and JAK2 genes in its pathogenesis, much like myelofibrosis does." (PMID 38319731, 2024). "Ruxolitinib, a non-selective JAK1/2 inhibitor approved for the treatment of myelofibrosis, reduces JAK-signal transducer activation and lowers STAT transcription signaling." (PMID 38429288, 2024). "However, JAK1 and JAK2, which are upstream of STAT3, have been mainly demonstrated to play a role in blood system diseases such as myelofibrosis and lymphoma." (PMID 35382859, 2022). "Additional JAK1/2 inhibitors, pacritinib, gandotinib, lestaurtinib, and momelotinib, are in clinical trials for myelofibrosis, myeloid neoplasms, or relapsed lymphomas, but they have not yet been investigated clinically in breast cancer patients." (PMID 34066153, 2021). "Therefore, we tested the role of feed-forward cytokine receptor signaling in BCG responses by blocking JAK1/2 using INCB0184224 (also known as Ruxolitinib, clinically approved for the treatment of myelofibrosis, and referred to here as JAKi)." (PMID 28751891, 2017). "We recently showed that the JAK inhibitor ruxolitinib, which also has relative selectivity for JAK1 and JAK2 and is currently approved for myelofibrosis, reversed disease in three AA patients in an open-label clinical trial of oral drug in moderate-to-severe disease." (PMID 26137574, 2015). "Ruxolitinib, the JAK1/2 inhibitor we used in vivo, is approved by FDA for treating myelofibrosis." (PMID 26687007, 2015). "Ruxolitinib (Jakafi), a non-selective inhibitor of JAK1 & 2, has been approved by FDA for patients with intermediate to high risk primary or secondary myelofibrosis." (PMID 24252238, 2013). "Most notable among these drugs is the JAK1/2 selective inhibitor ruxolitinib (INCB018424), which has shown promising results and relatively low toxicity in phase I/II clinical testing of patients with primary myelofibrosis." (PMID 22319590, 2012). "Moreover, MEK1/2 and ERK1/2 activation overcomes JAK1/2 inhibition in vivo in MPN mouse models and the administration of MEK1/2 or ERK1/2 inhibitors in combination with Ruxolitinib displayed superior therapeutic efficacy in vivo by reducing splenomegaly, disease burden and myelofibrosis." (PMID 36928007, 2023).
melanoma (119 papers, 2014 to 2025). A malignant, usually aggressive tumor composed of atypical, neoplastic melanocytes. "A study indicated that melanoma patients with high tumor burden and JAK1/2 mutations are insensitive to PD-1/PD-L1 blockade, partly because the JAK1/2 mutation hindered the adaptive upregulation of PD-L1 when exposed to IFN-γ57." (PMID 40861801, 2025). "In follow-up samples obtained from patients with melanoma who experienced tumor progression after an initial positive response, a homozygous mutation in JAK1/2 was identified." (PMID 40075727, 2025). "Although melanoma cells can still be recognized by T-cells, mutations in JAK1/2 render them resistant to the effects of IFN-γ." (PMID 40108693, 2025). "Their research identified JAK1/2-inactivating mutations in one of 23 melanoma tumor biopsies and in two of 48 human melanoma cell lines." (PMID 39534873, 2024). "Acquired resistance to PD-1 blockade in patients with advanced melanoma can be associated with loss-of-function mutations with loss of heterozygosity in JAK1/2 or in B2M." (PMID 39530091, 2024). "HT55 (CRC) and K2 (melanoma) cell lines harbored homozygous Glu1051Gln and Ala760Val putative JAK1 LOF missense mutations, respectively." (PMID 36669486, 2023). "Defects in IFNγ signaling (which also prevent IFNγ-induced MHC expression) have been identified in 4–10% of PD1-resistant melanomas and are often due to loss-of-function mutations in the IFNγ effector kinases JAK1 and JAK29,16." (PMID 36934113, 2023). "By contrast, CD8+ T cells failed to arrest at all and were always highly motile in MHC-deficient HCmel12 Jak1-KO melanomas." (PMID 37316667, 2023). "Namely, JAK1/2 mutations were associated with decreased Interferon-γ (IFN-γ) sensitivity of melanoma cells, and mutations in the gene encoding beta-2-microglobulin (B2M) to loss of surface expression of MHC-I and decreased antigen presentation." (PMID 35432344, 2022). "Inactivating JAK1/JAK2 mutations are detected in some tumor types (particularly melanoma), making these mutations candidates for observed ICB resistance." (PMID 34385592, 2022). "In melanoma, mutations in the JAK1/2 signaling pathway as well as JAK1/2 inhibition increase sensitivity to VSV-dM51." (PMID 34298601, 2021). "Here, the authors show that loss of IFNGR2 or JAK1 in a melanoma cell line enhances T cell mediated lysis, however these cells are paradoxically more sensitive to immune-mediated tumor control in vivo due to the loss of PD-L1." (PMID 32001684, 2020). "JAK1 or JAK2 inactivating mutations have been described in melanoma patients that prevent IFN-γ signaling, PD-L1 expression, and acquired resistance to anti-PD-1 therapy." (PMID 33419311, 2020). "We also found that loss of JAK1 in melanoma decreased the cytotoxicity of effector T-cells and expression of associated molecules such as TNF-α, granzyme, and perforin." (PMID 30837996, 2019). "In melanoma, loss-of-function JAK1/JAK2 mutations were discovered in a minority of patients after relapse on the anti-PD-1 treatment pembrolizumab; therefore, it is a potential avenue of acquired resistance to immune checkpoint blockade." (PMID 30986992, 2019). "Recent studies have shown that ∼30% of both melanoma and lung carcinomas have at least one mutation in the IFNγ pathway, including JAK1, IFNGR1, or IFNGR2, and resistance to checkpoint inhibitors in patients is associated with JAK1/2 mutations." (PMID 31133614, 2019). "Four melanoma patients treated with pembrolizumab were found to have loss of function mutations in JAK1/2 in relapsed tumors." (PMID 35582566, 2019). "Recently, JAK1/2 deficiency was demonstrated to protect melanoma cells from antitumor IFN-γ activity and results in T-cell-resistant melanoma lesions." (PMID 29780381, 2018). "Our studies in the three melanoma patient models identified allelic JAK1 and JAK2 losses as initial genetic alteration predisposing to IFNγ-resistance development." (PMID 28561041, 2017).
melanoma (continued). "Here we demonstrate that IFNγ-resistant melanoma clones with inactivating JAK1/JAK2 mutations frequently evolve in patients receiving different types of immunotherapy." (PMID 28561041, 2017). "Overall, these data demonstrated that JAK1 deficiency in Ma-Mel-61h cells was followed by silencing of antigen presentation, generating a T-cell-resistant melanoma phenotype." (PMID 28561041, 2017). "Our data demonstrate that JAK1/2 deficiency protects melanoma from anti-tumour IFNγ activity and results in T-cell-resistant HLA class I-negative lesions." (PMID 28561041, 2017). "In our patient models, JAK1 deficiency originated from an initial chromosome 1p aberration causing mono-allelic JAK1 loss in melanoma cells and a subsequent mutation inactivating the remaining JAK1 allele." (PMID 28561041, 2017). "In contrast to the JAK1/2-deficient melanoma cells, STAT1 mutant cells were established from a treatment-naive stage III lymph node metastasis suggesting that in this case spontaneous anti-tumour T-cell responses enriched these cells." (PMID 28561041, 2017). "Independent of existing exome data, Sanger sequencing revealed a JAK1 mutation in a cell line from melanoma patient Ma-Mel-61." (PMID 28561041, 2017). "Therapeutically, loss of JAK1 or MHCI pathway genes was shown to be associated with adaptive resistance to single agent pembrolizumab in a recent study of four relapsed melanoma patients." (PMID 29121062, 2017). "Acquired resistance to anti-PD-1 ICI in patients with melanoma has been reported to be associated with defects in the pathways involving interferon-receptor–associated Janus kinase 1 (JAK1) or Janus kinase 2 (JAK2), as well as in the antigen-presenting protein beta-2-microglobulin (B2M)." (PMID 40236650, 2025). "IFNs can improve ICI responses as loss-of-function mutations in IFN signaling components (i.e., JAK1/2) have been identified in melanoma patients after pembrolizumab treatment relapse, and knockout of IFN pathway mediators such as Jak1, Stat1, Ifngr1 in tumors can weaken ICI treatment efficacy." (PMID 39663510, 2025). "By analyzing melanoma tumor biopsies that relapsed after PD-1 treatment, acquired homozygous loss-of-function mutations were identified in the kinases associated with the interferon-gamma receptor pathway: Janus kinase 1 (JAK1) and Janus kinase 2 (JAK2)." (PMID 38903504, 2024). "Specifically, in a study of four patients with melanoma whose disease initially responded to anti-PD-1 treatment but relapsed months to years later, two patients had homozygous loss-of-function mutations in their Janus kinase 1 (JAK1) or JAK2 genes." (PMID 37287968, 2023). "In the study of four melanoma patients with AR to pembrolizumab, the resistant tumors of two patients were found to harbor JAK1 or JAK2 truncating mutation combined with LOH, leading to the biallelic loss of function, while no JAK1/2 mutations were seen in the baseline tumors." (PMID 34194441, 2021). "JAK1/2-deficient cells emerged under/after ICB in patients with advanced melanoma and obtained resistance to PD-L1 blockade, which may result from pre-existing heterogenous subclones or through an adaptive response." (PMID 34620200, 2021). "Mutations in cancers other than HCC associated with a negative outcome for ICI treatment include inactivating mutations in JAK1/2 or beta-2-microglobulin in melanoma, MDM4 amplifications, or EGFR alterations in different stage IV tumors or STK11/LKB1 alterations in KRAS-mutant lung adenocarcinoma." (PMID 33353145, 2020). "Whole exome sequencing of refractory melanoma tumor lesions of patients initially responding to anti–programmed death 1 (PD-1) therapy revealed loss-of-function mutations in the IFNyR-associated genes Janus kinase 1 (JAK1) and Janus kinase 2 (JAK2)." (PMID 31196219, 2019). "In addition, IFN-γ-resistant human melanoma cells with JAK1 or JAK2 mutation were resistant to the cytotoxic effects of T-cells." (PMID 30837996, 2019).
melanoma (continued). "In addition, loss-of-function mutations in Janus kinase 1 (JAK1) or Janus kinase 2 (JAK2) can lead to resistance to PD-1 therapy in melanoma by blocking the IFN-γ signal." (PMID 31824840, 2019). "Given the association of JAK1 mutation and loss of the wild-type allele with an acquired resistance to PD-1 blockade in melanoma, this homozygous mutation may create the similar clinical context in TNBC." (PMID 29996881, 2018). "Moreover, murine B16 melanoma cells deficient in JAK1 or IFNGR1 grew faster than control B16 cells in response to immune therapy." (PMID 29977240, 2018). "Interestingly, our data demonstrate that IFNγ-resistant JAK1/2-deficient melanoma cells progress to a ‘higher level' of immunotherapy resistance." (PMID 28561041, 2017). "Indeed, we demonstrated that JAK1/2 loss protected melanoma cells from anti-proliferative and pro-apoptotic IFNγ activity." (PMID 28561041, 2017). "Allelic JAK1/2 losses predisposing to IFNγ resistance development are frequent in melanoma." (PMID 28561041, 2017). "In this study, the authors show that melanoma patients can become resistant to immunotherapy by acquiring chromosomal alterations and subsequent inactivating mutations in genes of the IFNγ signalling cascade, most often JAK1 or JAK2." (PMID 28561041, 2017). "In addition, JAK1 Asp775Asn has been independently verified as a LOF variant in melanoma." (PMID 36669486, 2023). "Based on these findings, the role of the JAK1/STAT1 pathway in MBP-treated melanoma cells was experimentally validated by Western blot analysis." (PMID 40508400, 2025). "Network pharmacology analysis combined with experimental validation indicated that MBP exerts its anti-melanoma effects through multiple targets and pathways, prominently involving the JAK1/STAT1 signaling pathway." (PMID 40508400, 2025). "In this respect, the preferential contribution of JAK1 over JAK2 to the induction of PD-L1 by IFN-γ in melanoma cells has been reported." (PMID 40108693, 2025). "Loss-of-function mutations in members of the JAK family of proteins, JAK1 and JAK2, have been reported as mechanisms of both primary and acquired resistance to ICIs, particularly PD-1 blockade immunotherapy, in melanoma patients." (PMID 39534873, 2024). "In a study of melanoma with acquired resistance to ICI, JAK1-mutated melanoma cell lines were resistant to both Type I and II IFN signaling, while JAK2-mutated cells were resistant to Type II IFN but responded to Type I IFN signaling." (PMID 39802951, 2024). "Robust in vivo growth of HCmel12 Jak1-KO melanoma cells required antibody-mediated depletion of natural killer (NK) cells before tumour inoculation, in line with the known ability of NK cells to directly recognize and kill MHC-I-deficient cells by cytolysis." (PMID 37316667, 2023). "The transcriptomic profiles of melanoma and microglia cells were compared to determine differences in the JAK1/STAT3 signaling pathway." (PMID 37296634, 2023). "At the genomic level, IFNGR has high mutation frequency of 12%, comparable with JAK1, JAK2, and IRF1, in melanoma patients resistant to anti-CTLA4 therapy." (PMID 37275859, 2023). "For example, in melanoma, mutations in JAK1/JAK2 (Janus Kinase 1/2) and B2M (beta-2-microglobulin) genes associated with acquired resistance to ICIs, and STK11/LKB1 mutations in KRAS mutated lung adenocarcinoma, have been documented." (PMID 38136385, 2023). "In experiments inspired by these observations, we found that the nitric oxide donor S-nitroso-N-acetylpenicillamine (SNAP) effectively induced death of both IFN-responsive HCmel12 Ciita-KO and IFN-unresponsive HCmel12 Jak1-KO melanoma cells in vitro." (PMID 37316667, 2023). "JAK1/2 signaling is necessary to mount effective anti-tumor responses, which in turn are required to slow the growth of Ctrl compared to βA-expressing melanoma." (PMID 38304252, 2023).